CXCL12 (C-X-C motif chemokine ligand 12)
Diseases named in the same sentence as CXCL12 in open-access papers (continued):
Sharing a sentence is not in itself a finding about the gene and the disease.
cancer (continued). "Later on, the enhanced expression of the SASP factors CXCL12, HGF, MMPs and TGFβ in irradiated fibroblasts was reported to increase EMT and invasiveness of cancer cells, and enhanced expression of the SASP factors EGF, FGF-4, GM-CSF, IGF-1,2, IGFBP-2,4,6 induced chemoradioresistance in cancer cells." (PMID 32384619, 2020). "Finally, we found drugs targeting MSTN, CXCL12, and CAMK2B, which may be considered for the development of novel therapeutic strategies for cancer cachexia." (PMID 31013615, 2019). "Indeed, we have previously demonstrated that CXCL12 either induces HB-EGF shedding in monocytes, which in turn phosphorylates HER1 in bystander cancer cells, and transinhibits HER1 via intracellular G protein-dependent signaling in CXCR4/HER1 double-positive cells." (PMID 29989007, 2018). "Moreover, secreted factors (for example, thrombospondin 1 (THBS1) and biglycan (BGN)), and growth factors and cytokines (for example, TGFβ, CXCL12/SDF1, CTGF and FGF2), many of which actively control endothelial and cancer cell behaviour, were differentially regulated between iNFs and iCAFs." (PMID 28198360, 2017). "CXCL12, which encodes the ligand for CXCR4, was not among the chemokine genes we identified whose expression correlated with expression of CXCR4 in the ACC metastases, nor did we find CXCL12 in the cancer cells by IHC." (PMID 29088715, 2017). "The recruitment of CAF is induced by diverse cytokines that secreted by cancer cells and other stromal cells, including transforming growth factor-β (TGFβ), epidermal growth factor (EGF), platelet-derived growth factor (PDGF) and fibroblast growth factor 2 (FGF2), CXCL12 and so on30." (PMID 27922075, 2016). "An exception may be the expression of CXCR4, involved in the chemo attraction of cancer cells to CXCL12-rich environments, but not exclusively bone (e.g., brain also)." (PMID 27618899, 2016). "CXCL12/CXCR4 is a critical signaling pathway in the regulation of leukocyte recruitment and embryo development and has recently been demonstrated to play important roles in cancer invasion, metastasis, angiogenesis, cancer cell-microenvironment interaction and chemoresistance." (PMID 25679210, 2015). "To explore the novel role of the CXCL12/CXCR4 axis in PNI, we evaluated the representative immunohistochemical staining properties of CXCR4 and CXCL12 in the resected PCa specimens accompanied by PNI, where the staining of S100 served as a nerve tissue marker and CK19 served as a cancer cell marker." (PMID 25605248, 2015). "Moreover, the reduction of the expression level of CXCR4 in the metastasized cancer cells is not dependent on the expression level of CXCL12 in the lung tissue around the metastasized cancer cells." (PMID 26083776, 2015). "Moreover, CXCL12 and a CCR7 ligand, CCL21, can induce the resistance of cancer cells to anoikis, which is a major hindrance to the metastatic spread of various types of cancer, by regulating proapoptotic Bmf and antiapoptotic Bcl-xL proteins." (PMID 24966464, 2014). "Considering the upregulated expression of spinal CXCL12 began at day 3, about two days prior to the detectable onset of cancer pain-related behaviors, we hypothesized that TCI-induced rapid-onset increase of endogenous CXCL12 may contribute to the induction of BCP." (PMID 24735601, 2014). "The prevailing model of cancer metastasis is that malignant tumors spread to distant tissues through the over-expression of CXCR4, thereby sensitizing malignant cells to spread in response to distant gradients of CXCL12 produced by metastatic destination organs." (PMID 24594697, 2014). "However, CXCR4 and CXCR7 expression has been reported to have an intracellular location in other cancers such as gallbladder and pancreas without CXCL12 stimulation." (PMID 24497931, 2014).
cancer (continued). "Based on the well-characterized roles of CXCL12 and CXCR4 in chemotaxis and the similarities between chemotactic cell migration and cancer cell movement to distant sites, this receptor-ligand pair has been hypothesized to play a role in cancer pathogenesis and metastasis." (PMID 23322021, 2013). "Cancer cells undergoing angiogenic switch also produce chemoattractants and mitogens, including HIF1-α (hypoxia-inducible factor 1-alpha), VEGF, FGF-1, CCL2 (C-C motif chemokine 2), and CXCL12 (stromal cell-derived factor 1), for endothelial cells and proangiogenic immune cells." (PMID 23717341, 2013). "Thus, CXCL12 and HB-EGF induced GM-CSF expression in HeLa and DLD-1 cancer cells." (PMID 20946648, 2010). "The chemotactic effect on multiple cell lines by CXCL12 and its receptors might indicate the global importance of CXCL12/CXCR4, 7 chemokine axis in the modulation of cell migration and mediates cross‐talk as well as the interaction between immune and cancer cells." (PMID 29105376, 2018). "The system was used to illustrate paracellular trans-endothelial migration of individual cancer cell expressing CXCR4, without degrading the endothelium, in response to CXCL12 chemokine gradients." (PMID 39459070, 2024). "A limitation of this study is that tasquinimod, the inhibitor for S100A9, and AMD3465, which blocks the cell surface binding of CXCL12 to CXCR4, are currently under clinical trial and has been not approved for cancer therapy yet." (PMID 35304461, 2022). "Although CXCR4 antagonists have already been tested in clinical trials in other type of cancers, demonstrating that blocking CXCL12 binding to CXCR4 can interfere with cancer progression, specific blockers of CXCL12 production are still lacking." (PMID 34834449, 2021). "COL6A3, COL8A1, CDH11, and CXCL12 were not expressed in either PDAC tissues or normal tissues, and BGN and THBS2 were overexpressed in both cancer and normal tissues." (PMID 33282565, 2020). "On the other hand, the information regarding CXCR4/CXCL12 axis during the development of FMC is almost absent, despite the fact FMC being considered as suitable cancer model." (PMID 30012106, 2018). "The CXCL12 analog peptide CTCE-9908 inhibits lung metastasis in mouse models and tests in Phase I/II clinical trials in cancer patients showed no major adverse effects." (PMID 26396176, 2015). "Due to the involvement of CXCL12/CXCR4 in migration, angiogenesis, and development, it is not surprising that this axis is often exploited by cancer cells for metastasis as well as survival and proliferation." (PMID 20661426, 2010). "The transcripts of the FAP and CXCL12 genes were detected only in IVP-9TS primary culture of human fibroblasts, which is consistent with the literature data on their predominant expression in CAFs, but not in cancer cells." (PMID 33804861, 2021). "In the context of CXCL12 activities in cancer, the review also addresses the roles of CXCR7 which is the other CXCL12 receptor; here, we describe the functions of CXCR7 alone or in the context of CXCR4, in regulating non-conventional cancer-related effects." (PMID 32582148, 2020). "However, there are no aptamers currently approved for cancer therapy, probably due to their rapid clearance, and only two aptamers (AS1411 against nucleolin and NOX-A12 against CXCL12) are in clinical trials for cancer therapy." (PMID 31470510, 2019). "As a whole, it is therefore evident that, regardless of the exact mechanism leading to CXCL12/CXCR4/ACKR3 over-expression/stimulation in cancer, this axis plays multiple fundamental roles in cancer progression and as such, offers an important potential target for disease treatment." (PMID 30257500, 2018). "In the immunohistological and flow cytometric analyses, the expression level of CXCR4 in the metastasized cancer cells was decreased compared with that in the cancer cells in orthotopic tumors, although the expression level of the CXCR4 ligand CXCL12 was not reduced in the lung." (PMID 26083776, 2015).
cancer (continued). "CXCR4 inhibition may not be sufficient to block the effects of CXCL12, which may also bind to CXCR7 on cancer or stromal cells." (PMID 26062132, 2015). "Accordingly, generation of two different sets of nonlinear ODEs let us describe cancer cell and fibroblast dynamics and could determine the critical time-points of switching in SLIT2 and CXCL12 genes which are essential for fibroblast status change from normal to cancer associated type." (PMID 32384110, 2020). "However, even with these limitations, many of the findings discussed have been validated by the fact that the same chemokine systems appear to be involved in mediating bone metastasis regardless of the cancer of origin, in particular CCL2/CCR2, CCL3/CCR1, IL-8/CXCR1, and CXCL12/CXCR4." (PMID 29930538, 2018). "We then determined that SDF-1/CXCL12 treatment could further induce EMT in CD133+CXCR4+ cancer cells and enhance their invasive behavior, while this could not be observed in CD133+CXCR4- cancer cells." (PMID 22871210, 2012). "To evaluate this surprising lack of difference in adhesion selectivity, we next turned our attention to how CXCL12 and receptors CXCR4 and CXCR7 on the vascular endothelia, rather than on cancer cells, may be key determinants in the intravascular adhesion step of metastasis." (PMID 19484126, 2009).
infection (160 papers, 2005 to 2025). The state of being infected such as from the introduction of a foreign agent such as serum, vaccine, antigenic substance or organism. "Recent work has highlighted Cxcr4 as a mediator of host infection-associated angiogenesis, while this study further links the Cxcl12/Cxcr4 signalling axis to virulence-dependent neutrophil recruitment during mycobacterial infections." (PMID 33826679, 2021). "We have demonstrated a link between infection-associated upregulation of miR-206 and suppression of neutrophil recruitment to the site of pathogenic mycobacterial infection involving the Cxcl12/Cxcr4 signalling pathway." (PMID 33826679, 2021). "In vitro infection of astrocytes with lentivirus encoding both CXCL12 and mCherry confirmed transduction and CXCL12 expression as assessed by immunocytochemistry." (PMID 22933014, 2012). "By contrast, differentiating ES and MEF derived from 5T4 knockout (KO) mice show only intracellular CXCR4 expression but infection with adenovirus encoding mouse 5T4 restores CXCL12 chemotaxis and surface co-localization with 5T4 molecules." (PMID 20376365, 2010). "We show that host miR-206 is increased by pathogenic M. marinum to impede the host Cxcl12/Cxcr4 signalling axis, thereby reducing protective early neutrophil recruitment to the site of infection, aiding the creation of a permissive niche for mycobacterial infection." (PMID 33826679, 2021). "To confirm that CXCL12-resistant (RES) HIV variants are present at an advanced stage of infection, we next measured the effects of CXCL12 on CXCR4-using, recombinant viral populations generated from plasma of nine late diagnosed individuals with CD4TL count < 200/μl." (PMID 33872329, 2021). "In order to confirm whether CXCL12 rs1801157 polymorphism is associated with infection independently of confounding factors, data were adjusted for all confounding factors observed in the previous analysis in a binary logistic regression." (PMID 30227860, 2018). "Knowing that virus-induced inflammation in animal models and humans is associated with an increase in serum levels of G-CSF, a decreased local concentration of CXCL12 in the bone marrow may have been why VSV caused the otherwise unexpected release of CXCR4+ neutrophils by 24-h post-infection." (PMID 32882969, 2020). "Meanwhile, CXCL12 expression in endothelial cells was increased only after infection with SARS-CoV-2." (PMID 39773555, 2025). "CCL21 protein and mRNA remained low at day 3 post-infection, and Cxcl12 and Cxcl13 were also repressed." (PMID 39708807, 2025). "We detected genome-wide significant genetic associations with urinary bacterial relative abundances, in or near candidate genes including CXCL12, ABCC1, and ROBO1, which are implicated in urinary tract development and response to infection." (PMID 41364520, 2025). "We have observed that a reduction in miR-126 transcript alters normal macrophage phenotype and function through its involvement in the Cxcl12/Ccl2/Ccr2 axis and coupled with concurrent mTOR inhibition, increases cell death at the site of infection." (PMID 38307625, 2024). "KSHV infection differentially impacted host gene expression in KSX-476 and KSX-488; infection induced CXCL12 production from KSX-476." (PMID 39386738, 2024). "The results demonstrated that untreated A549 cells infected with B. pseudomallei expressed significantly higher amounts of MIF, PAI-1, IL-18, CXCL1, CXCL12 and IL-8 when compared with uninfected cells at 12 h post-infection." (PMID 36758060, 2023). "Systemic inflammation and infection down-regulate CXCL12 transcripts and protein levels in vivo, whereas reduced CXCR4 function (CXCL12 receptor) in B-cell progenitors impairs B lymphopoiesis." (PMID 36717247, 2023). "In this study, serum values of CXCL12 in domestic pigs following infection with the highly virulent isolate Georgia 2007/1 (104 HAD50/mL), alongside VEGFA and VEGFB serum levels (described later in Section 2.11), were evaluated." (PMID 36680273, 2023).
infection (continued). "The similar expression trends of the genes were observed, as EgPSC infection upregulated the mRNA levels of Cldn8, and downregulated the mRNA levels of Pklr, Cldn4 and Cxcl12." (PMID 36713407, 2022). "Collectively, the CXCL12/CXCR4 axis can have important pathophysiological roles in infection‐induced PTL." (PMID 35318804, 2022). "Infection with L. monocytogenes causes H3K18 deacetylation of many genomic proteins in colon cells, including SMAD1, IRF2, SMARCA2, and CXCL12." (PMID 35572672, 2022). "Recruitment of inflammatory cells to damaged tissues after infection or injury relies on the interaction of the fully reduced form of HMGB1 with the chemokine C-X-C Motif Chemokine Ligand 12 (CXCL12)." (PMID 36071400, 2022). "Apart from IL-8 and CXCL12, the levels of secreted cytokines were higher at later timepoints of infection." (PMID 35967370, 2022). "Expression of CXCL12 in the endothelium allows recruitment and transmigration of cells across the vessel wall to areas of infection and inflammation." (PMID 36239312, 2022). "Other Cm infection induced cell migration/homing immune molecules were also affected by miR135-a mimic transfection including reduced CXCL12 (6.33 ± 0.84 to 2.65 ± 0.42), and CCR5 (29.13 ± 0.89 to 23.43 ± 0.11)." (PMID 33928045, 2021). "In contrast, there was a significant reduction or failure in activation of type 2-related chemokines/cytokines (Cxcl12, Ccrl1, Il4, Il23a) and signature markers (Stat3, Stat5b, Stat6, Mrc1, Ahr) during infection." (PMID 34320039, 2021). "We found pathogenic mycobacteria trigger the host to produce more miR-206 in order to suppress the otherwise protective recruitment of neutrophils to sites of infection via the host Cxcl12/Cxcr4 signalling pathway." (PMID 33826679, 2021). "The infection increased a key cytokine, CXCL12, known to be involved in inflammatory responses in the pancreas." (PMID 34282405, 2021). "The analysis of the expression of these molecules revealed increased expression of Ccl25, Cxcl12 and P-selectin in the thymus, and decreased expression of Ccr7 in BM cells upon M. avium strain 25291 infection." (PMID 34987496, 2021). "Increased transcription of Elmo1 following miR-206 knockdown is likely to increase neutrophil mobility during infection in cooperation with increased Cxcl12/Cxcr4 signalling." (PMID 33826679, 2021). "The expressions of MIF, XCL1 and CXCL12 decreased at the early stage of infection, indicating IBV affects macrophage chemotaxis." (PMID 33509253, 2021). "Overall, these results confirm that viruses with increased resistance to CXCL12 are frequent at a late stage of infection in patients with low CD4TL levels." (PMID 33872329, 2021). "After infection of human bronchial epithelial cells with sh-CXCL12 lentivirus, BEAS-2B and HBE cells were induced with OVA to produce inflammation." (PMID 34118928, 2021). "Unrelated recombinant viral populations from plasmas of patients at the chronic stage of infection were also highly sensitive to CXCL12." (PMID 33872329, 2021). "We tested the capacity of CXCL12 to inhibit infection of CD4TL with viruses pseudotyped with Envs of virus clones isolated from PBMCs of 5 patients (P) of the Amsterdam cohort (ACS), three treatment naïve, two under AZT monotherapy." (PMID 33872329, 2021). "In this study we have demonstrated an in vivo link between infection-induced miR-206 expression and the Cxcl12/Cxcr4 signalling axis in the control of mycobacterial infection." (PMID 33826679, 2021). "To this end, we repeated infection assays of CD4TL with RES or SENS viruses in the presence of P2G, a CXCL12 variant that binds CXCR4 with comparable affinity compared to CXCL12 but does not internalize the receptor." (PMID 33872329, 2021). "SDF-1α, also called as C-X-C motif chemokine 12 (CXCL12), is a homeostatic chemokine that has recently attracted much attention in the immune system, inflammation/infection, nervous system, tissue damage, and hematopoiesis research." (PMID 32344892, 2020).